TLR2 (toll like receptor 2)
Diseases named in the same sentence as TLR2 in open-access papers (continued):
Sharing a sentence is not in itself a finding about the gene and the disease.
pulmonary tuberculosis (27 papers, 2008 to 2026). A bacterial infection that affects the lungs and is caused by Mycobacterium tuberculosis. "This systematic review evaluates the role of TLR2 polymorphisms in influencing susceptibility to and clinical manifestations of pulmonary TB." (PMID 42075681, 2026). "In conclusion, TLR2 genetic polymorphisms significantly increase the risk of developing pulmonary TB and contribute to more severe clinical outcomes." (PMID 42075681, 2026). "In this genetic analysis of the TLR2 polymorphisms, we newly identified an association between the specific haplotype [A-G-(Ins)-T] and susceptibility to pulmonary TB in the Taiwanese population." (PMID 20113509, 2010). "At the molecular level, a TLR2 polymorphism appears to be associated with TB susceptibility in Asians, but not in Caucasians, and inflammatory mediator levels are associated with ethnicity in pulmonary TB patients of African and Eurasian ancestry." (PMID 29787561, 2018). "Moreover, recent studies demonstrated a direct association between TLR2 polymorphisms and enhanced bacterial loads in pulmonary tuberculosis patients." (PMID 27494953, 2016). "A total of 368 subjects, including 184 patients with pulmonary TB and 184 healthy controls, were examined for TLR2 polymorphisms over locus -100 (microsatellite guanine-thymine repeats), -16934 (T>A), -15607 (A>G), -196 to -174 (insertion>deletion), and 1350 (T>C)." (PMID 20113509, 2010). "We observed an association between the specific TLR2 haplotype and susceptibility to pulmonary TB." (PMID 20113509, 2010). "TLR2 genetic polymorphisms influence susceptibility to pulmonary TB." (PMID 20113509, 2010). "However, these do not generally confound genetic associations except through selection bias or modification of the TLR2 gene-pulmonary TB association." (PMID 20113509, 2010). "Here we show that differences exist in the expression of a surface protein (Toll-like receptor 2) between macrophages recovered from the sputum of individuals in different diagnostic groups: i.e., infection free, latent tuberculosis infection, and active pulmonary tuberculosis." (PMID 29104936, 2017). "Although synonymous SNPs in the coding region of the TLR2 gene have been associated with tuberculous meningitis in patients in Vietnam, there are no reports of the association between variants of this gene and the development of systemic symptoms of or pleural involvement in pulmonary TB." (PMID 20113509, 2010). "The aim of the present study was to examine whether the genotypes defined by the 5 TLR2 gene polymorphisms located at -16934, -15607, -196 to -174, -100, and 1350 influence susceptibility to pulmonary TB, its clinical presentations, and peripheral blood lymphocyte subsets at diagnosis." (PMID 20113509, 2010). "In this study, we tried to find the association of polymorphisms of TLR2, TLR8, and four polymorphisms of the VDR gene (FokI, TaqI, ApaI, and BsmI) with pulmonary TB progression in the Kazakh population." (PMID 38398882, 2024). "The methylation of certain CpG sites in the TLR2 promoter has been shown to reduce expression levels in natural killer cells/monocytes of patients with active pulmonary tuberculosis and correlates with bacterial load and disease severity." (PMID 39339847, 2024). "Contrary, RAGE is protective against the development of pulmonary TB in mouse models in line with reduction of antimicrobial activity in human macrophages upon TLR2/1 ligand activation by S100A12 knockdown." (PMID 32849645, 2020). "The down-regulation of TLR2 expressions through aberrant DNA methylation of certain CpG sites over TLR2 promoter region has been demonstrated in patients with active pulmonary tuberculosis (TB) disease and cystic fibrosis." (PMID 32069296, 2020). "Publications regarding the associations of toll-like receptor 2 (TLR2) G2258A and T597C polymorphisms with pulmonary tuberculosis (PTB) susceptibility are inconsistent." (PMID 24124467, 2013).
pulmonary tuberculosis (continued). "We carried out a case–control association community based study, genotyping 12 polymorphisms of TLR2, TLR4, TLR6 and TLR9 genes in 90 patients with confirmed pulmonary TB and 90 unrelated exposed but asymptomatic household contacts." (PMID 24053111, 2013). "Polymorphic loci rs5743708 (TLR2) influence the risk of developing LTBI and subsequent pulmonary tuberculosis in the Chinese population, and variations in rs7873784 (TLR4) and rs5743836 (TLR9) influence the risk of developing LTBI and pulmonary tuberculosis." (PMID 39339847, 2024). "The analysis revealed the association of TLR2 “CC” genotype (rs3804100C/T) and TLR9 “TC” genotype (rs5743836) with LTBI susceptibility and TLR2 “GA” genotype (rs5743708A/G), TLR4 “GG” genotype (rs7873784C/G) and TLR8 “CC” genotype (rs3764879C/G) with susceptibility to pulmonary TB." (PMID 30167433, 2018). "Whereas, a Chinese cohort study observed association of TLR2 rs3804099 T/C with susceptibility to tuberculous meningitis rather than with susceptibility to pulmonary TB." (PMID 30167433, 2018). "In addition, the prevalence rate of TLR2 2258 SNP was reported to be increased in patients with pulmonary TB alone, as well as with definitive pulmonary plus extrapulmonary TB, as compared to cases with latent TB infection." (PMID 28118851, 2017). "In brief, we found previously that the TIRAP SNP C558T and the TLR-2 SNP T597C were associated with susceptibility to meningeal rather than pulmonary tuberculosis and this was reconfirmed in the current dataset." (PMID 18369480, 2008). "Therefore, we examined whether polymorphisms in TLR2, TLR4, TLR6 and TLR9 are associated with the susceptibility to pulmonary TB in Mexican individuals from a rural area with high incidence of TB." (PMID 24053111, 2013). "There was no allelic association between TLR2 T597C and pulmonary TB caused by non-Beijing isolates (control vs. pulmonary non-Beijing: OR = 1.00 [95% CI 0.71–1.43] P = 0.991) or for Beijing isolates (control vs. pulmonary East-Asian/Beijing: OR = 1.27 [95% C.I. 0.82–1.47], P = 0.264)." (PMID 18369480, 2008).
candidiasis (26 papers, 2007 to 2025). Infection with the organism Candida. "While TLR2 has been shown to be essential for defense against C. albicans, contrasting results were reported with TLR2 KO mice being resistant to candidiasis whereas TLR4 KO mice were susceptible." (PMID 18606009, 2008). "TLR2 recognizes C. albicans phospholipomannans and TLR2 deficiency impairs neutrophil chemotaxis, phagocytic activity, and cytokine and chemokine production resulting in reduced survival during systemic candidiasis in mice." (PMID 34964702, 2022). "Moreover, TLR2 deficiency influences susceptibility to systemic candidiasis in mice." (PMID 41295183, 2025). "The recognition of hyphae by TLR2 is associated with the induction of a Th2 response, which is not protective but could be involved in the regulation of the inflammatory response, since mice that lack TLR2 are resistant to systemic candidiasis." (PMID 24106515, 2013). "Variants in TLR2 and TLR4 have been associated with altered immune responses to Candida infections, suggesting that genetic predisposition plays a role in the pathogenesis of RVVC." (PMID 41295183, 2025). "Similar to these previous results, we found a significant decrease in the gene expression of TLR2 in the candidiasis group." (PMID 38525710, 2024). "TLR2 plays a significant role in conferring protective immunity against Candida infection at mucosal sites, including gastrointestinal and reproductive tracts by inducing Th17 differentiation through MyD88 signaling." (PMID 36177012, 2022). "The gene coding for Toll-like receptor 2 (TLR2), critical for immune responses during candidiasis, was predominantly upregulated in response to C. glabrata, C. parapsilosis, and C. tropicalis (and, to a lesser degree, C. albicans)." (PMID 33024045, 2020). "Here, we extend our previous in vitro studies to an ex vivo model in order to demonstrate that systemic candidiasis or TLR2 agonist exposure in vivo impacts the antifungal phenotype of the macrophages produced in vitro from purified HSPCs." (PMID 30234030, 2018). "Beside epithelial cells dermal fibroblast enhance the skin antimicrobial defense during Candida infection upon activation through Toll-like receptor 2 (TLR2) and IL-1β secretion." (PMID 29371576, 2017). "By contrast, in a systemic infection model of candidiasis, TLR2-mediated recognition of Candida triggers IL-10 production and decreases Th1 polarisation." (PMID 23189270, 2012). "The contribution of TLR signaling, especially via TLR2, and collaboration with dectin-1 signaling has previously been recognized in cytokine responses in Candida infections." (PMID 21283787, 2011). "While TLR2 has been shown to be essential for immune responses in macrophages, TLR2 KO mice were found to be resistant to candidiasis." (PMID 18606009, 2008). "In the case of Candida infection, TLR2 induced proliferation and survival of regulatory T cells, which appeared largely responsible for the increased IL10 release induced by TLR2." (PMID 17676990, 2007). "In addition, qPCR analysis revealed a significant decrease (p < 0.0001) in the mRNA expression of TLR2 in the candidiasis group relative to that in the control group." (PMID 38525710, 2024). "Therefore, we conclude that the TLR2 agonist induced protection against candidiasis is at least partially mediated by the expansion of hematopoietic progenitors." (PMID 30234030, 2018). "Moreover, TLR2−/− mice had significantly impaired survival to Candida infection, indicating that TLR2 confers protection against primary disseminated candidiasis." (PMID 28289440, 2017). "The deficiency of TLR2 influences susceptibility to systemic candidiasis in mice, but no studies have been performed in vaginal candidiasis models." (PMID 25295030, 2014). "However, the role of TLR2 in controlling systemic candidiasis seems to be fungal strain specific." (PMID 36177012, 2022).
candidiasis (continued). "However, other studies have shown a dispensable role for TLR2 during systemic candidiasis, which may be explained by the differential dependence of different C. albicans strains on TLR2 recognition." (PMID 34964702, 2022). "However, immunodepletion of c-Kit+ progenitors in TLR2 agonist-treated mice abrogates protection against tissue invasion during candidiasis, despite their similar amount of mature myeloid cells in the spleen at the moment of infection, than isotype control injected mice." (PMID 30234030, 2018). "Upon Candida infection, NLRP3-mediated inflammasome assembly is induced by key pattern recognition receptors and their downstream molecules, including TLR2, Dectin-1, Syk and ZBP142–44,105." (PMID 34795266, 2021). "Of the TLRs, TLR2 and TLR4 play important roles in the pathogenesis of candidiasis, such that they induce proinflammatory responses in a synergistic manner with specific CLRs." (PMID 33919079, 2021). "CLRs, such as Dectin-1 and DC-SIGN; TLRs, such as TLR2 and TLR4; and other receptors such as Galectin-3 and CR3 have all been shown to play a role in Candida infection." (PMID 33562068, 2021). "Among the TLR family, mainly TLR2 and TLR4, are involved in the host interaction with C. albicans and play a significant role in the development of host immune responses during candidiasis." (PMID 24391778, 2013). "A recent study demonstrated that a wild-type strain of Candida induced TLR2, TLR4, TLR6, and TLR9 gene expression activation in the epithelial cells showing that different receptors may play important roles in candidiasis." (PMID 32466609, 2020). "Although TLR-2 signaling promotes Treg proliferation during systemic candidiasis, IL-17A induction was not assessed in Tregs during the infection." (PMID 25790134, 2015). "By contrast, in an intraperitoneal model of candidiasis, clearance is impaired 1 day afterinfection in the absence of TLR2." (PMID 23189270, 2012). "Upon intravenous Candida infection, absence of Tregs results in improved fungal clearance 7 days after infection and better survival of TLR2−/− mice when compared to wild-type mice." (PMID 23189270, 2012). "Furthermore, TLR2 and TLR4 have previously been reported to mediate host response to other fungi such as candidiasis, Aspergillus, and Cryptococcus neoformans." (PMID 17982419, 2007). "Zymosan, a polysaccharide originating from the yeast Saccharomyces cerevisiae, can be detected by TLR2/6, while TLR2 and TLR4 are involved in the host interaction with C. albicans and play a significant role in the development of host immune responses during candidiasis." (PMID 40891672, 2025). "Interestingly, a newly generated population of inflammatory macrohages and a subset of DCs with the phenotype of moDCs were induced during candidiasis in wild-type mice, but not in TLR2−/− mice, indicating that development of both cell populations is TLR2 dependent." (PMID 21935459, 2011).
gout (26 papers, 2012 to 2025). A condition characterized by painful swelling of the joints, which is caused by deposition of urate crystals. "Furthermore, TLR2 signaling has been highly implicated in mediating gout pathogenesis." (PMID 33002030, 2020). "TLR2 was significantly overexpressed in all three DC subsets and monocytes of RA as compared with gout monocytes and DCs." (PMID 38601165, 2024). "By mediating the TLR2-MyD88 signaling pathway, it regulates the release of inflammatory factors and oxygen free radicals to prevent and treat gouty arthritis." (PMID 36330088, 2022). "rhPRG4 (200 μg/mL) reduced basal and TLR2 stimulated bead uptake by gout monocytes compared to IL-1RA (250 ng/mL) treatment (p<0.0001 for both comparisons)." (PMID 34992596, 2021). "Damage-associated molecular patterns (DAMPs) can also activate the NLRP3 inflammasome in gout and increase IL-1β gene expression via activation of toll-like receptors 2 and 4 (TLR2 and TLR4)." (PMID 34992596, 2021). "IL-1RA and rhPRG4 exhibited interesting differences in modulating normal and gout monocytes under basal and TLR2-stimulated conditions." (PMID 34992596, 2021). "After MSU crystals are recognized by toll-like receptor 2/4 in the early stages of gouty arthritis, uptake of MSU crystals by macrophages, mast cells, and synovial lining cells activates the NALP3 inflammasome." (PMID 34564665, 2021). "Triglycerides, the level of which was highly associated with VFO, are the source of fatty acids that stimulate toll-like receptor (TLR)-2 and can subsequently activate the inflammasome, which plays a central role in acute gout attacks." (PMID 25889813, 2015). "We stimulated PBMCs of patients with gout and of healthy donors with either the TLR2/6 ligand FSL-1 or TLR1/2 ligand Pam3Cys." (PMID 22762240, 2012). "Previous studies have shown that TLR2/4 activation amplifies inflammation in myeloid cells through NF-κB signaling, and the expression of these receptors correlates with disease activity in gout." (PMID 41583461, 2025). "We found higher TLR2 expression in SF cells from RA than in gout patients." (PMID 38601165, 2024). "Additionally, PA strongly eliminated inflammation and gout risk by downregulating macrophage and neutrophil invasion, as well as CXCL1 and TLR2 expressions." (PMID 39060811, 2024). "The current pathogenesis of gouty arthritis is primarily based on the following two main processes: activated NALP3 inflammasome assembly mechanism and the TLR2/4-NF-κB signal transduction pathway." (PMID 38652726, 2024). "In gouty arthritis with cartilage damage, inflammation is enhanced by activating the ITGB1-dependent TLR2/4-NF-κB signaling pathway." (PMID 37941009, 2023). "Extracellular UA and MSU have been recognized by TLR2 and TLR4 in gouty arthritis and activate the MAPK, NLRP3 and NF-κB signaling pathways, thus initiating the inflammatory response." (PMID 36438835, 2022). "Using flow cytometry, we quantified TLR2 expression on peripheral monocytes and neutrophils following exercise and MSU crystal-induced gout." (PMID 33002030, 2020). "The inhibitory effect of TLR2 and TLR4 neutralizing antibodies supports a role for TLR2 and TLR4 in mediating the initial steps of gout pathogenesis." (PMID 30157934, 2018). "The potential pivotal role of the components of innate immunity, especially TLR2/TLR4 and the NLRP3 inflammasome, in this disease, seems attractive as potential target candidates for the treatment of gout." (PMID 23738004, 2013). "The present study provides evidence that the PBMCs of patients with gout display a more prominent synergistic production of IL-1β after stimulation with MSU crystals and TLR-2/1 ligands, compared to healthy controls." (PMID 22762240, 2012). "Studies have shown that the absence of HDAC3 in macrophages alleviates MSU crystal-induced gout inflammation by inhibiting the TLR2/4-driven IL-6/STAT3 signaling pathway, suggesting that HDAC3 may serve as a potential therapeutic target for gout." (PMID 41311848, 2025).
gout (continued). "Together, these findings suggest that TLR2 and TLR4 are key drivers of IL-1 family cytokine signaling in gout and may play a central role in disease exacerbation." (PMID 40709261, 2025). "Deficiency of HDAC3 in macrophage alleviates MSU crystals-induced gouty inflammation through inhibition of TLR2/4 driven IL-6/STAT3 signaling pathway, suggesting that HDAC3 could contribute to a potential therapeutic target of gout." (PMID 38711064, 2024). "Under TLR2 stimulated condition, bead phagocytosis by normal monocytes increased (p<0.05) while gout monocytes showed no significant change in their bead uptake (p>0.05)." (PMID 34992596, 2021). "In the stage of acute gouty arthritis, the MSU crystal activates TLRs such as TLR2 and TLR4." (PMID 34803702, 2021). "Well-known for preserving cartilage integrity, recombinant human proteoglycan-4 exerts its anti-gout properties by restraining phagocytosis of MSU crystals, NF-κB nuclear translocation, and NLRP3 inflammasome activation in macrophages due to its interaction with CD44 (mainly) and TLR2/4 (partially)." (PMID 39935474, 2025). "Interestingly, expression of the NLRP3 inflammasome components was not affected by TLR2 priming or urate crystal activation in gout monocytes." (PMID 34992596, 2021).